FOXRED1 (FAD dependent oxidoreductase domain containing 1)
Description:
Required for the assembly of the mitochondrial membrane respiratory chain NADH dehydrogenase (Complex I). Involved in mid-late stages of complex I assembly.
Synonyms: FP634; H17; MC1DN19
Tractability: Antibody: UniProt predicts a signal peptide or a membrane-spanning region. PROTAC: ubiquitination databases record sites on it; its protein half-life has been measured.
Gene: Protein-coding gene on chromosome 11 (126,269,024 to 126,278,132, forward strand). Ensembl gene ENSG00000110074.
Subcellular location: Mitochondrion inner membrane
Subcellular location (Human Protein Atlas): Mitochondria
Pathways (Reactome):
Metabolism: Complex I biogenesis
Gene Ontology:
Biological process: mitochondrial respiratory chain complex I assembly
Cellular component: mitochondrial inner membrane; mitochondrion; cytoplasm
Genetic constraint (gnomAD): Loss-of-function variants: 37 observed, 43.55 expected, observed/expected ratio (o/e) 0.85, 90% interval 0.65 to 1.12. The upper end of that interval is the gene's LOEUF score, 1.12, which puts it in group 4 of 6, group 1 being the genes least tolerant of losing a copy. Missense variants: 521 observed, 577.93 expected, observed/expected ratio (o/e) 0.9, 90% interval 0.84 to 0.97. Synonymous variants: 238 observed, 229.56 expected, observed/expected ratio (o/e) 1.04, 90% interval 0.93 to 1.15.
Gene-disease validity (ClinGen):
ClinGen rates the evidence that FOXRED1 causes each of these diseases.
mitochondrial disease (autosomal recessive): Definitive.
Leigh syndrome (autosomal recessive): Moderate. A progressive neurological disease defined by specific neuropathological features associating brainstem and basal ganglia lesions.
Homologues: Orthologues: chimpanzee FOXRED1 (93% identical), macaque FOXRED1 (91% identical), pig FOXRED1 (84% identical), rabbit FOXRED1 (84% identical), dog FOXRED1 (83% identical), guinea pig FOXRED1 (80% identical), rat Foxred1 (80% identical), mouse Foxred1 (79% identical), tropical clawed frog foxred1 (60% identical), zebrafish foxred1 (58% identical), Drosophila melanogaster CG3270 (42% identical), Drosophila melanogaster l(2)37Bb (38% identical), and 1 more. Paralogues in human: DMGDH (21% identical), SARDH (21% identical), PDPR (17% identical), L2HGDH (14% identical), AMT (7% identical), YPEL3 (4% identical), YPEL1 (3% identical), YPEL2 (3% identical), YPEL4 (3% identical), YPEL5 (3% identical).
Diseases named in the same sentence as FOXRED1 in open-access papers:
FOXRED1 is named in the same sentence as 22 diseases in open-access papers, as found by Europe PMC text mining. Sharing a sentence is not in itself a finding about the gene and the disease. The quoted sentences say what the papers report.
colorectal cancer (3 papers, 2021 to 2026). A primary or metastatic malignant neoplasm that affects the colon or rectum. "While low FOXRED1 expression correlates with poor prognosis in colorectal cancer, NUBPL KD decreases cell invasion." (PMID 38898058, 2024). "FOXRED1 encodes a protein that contains a FAD-dependent oxidoreductase domain and has been investigated as a new biomarker in human colorectal cancer." (PMID 34733794, 2021).
Leigh syndrome (3 papers, 2021 to 2024). "Mutations in FOXRED1 have been reported to be associated with Leigh syndrome and infantile-onset mitochondrial encephalopathy." (PMID 33613441, 2021). "The mutation (FOXRED1:694C>T) is associated with Complex I deficiency, which leads to mitochondrial dysfunction and encephalopathy, as well as association with Leigh syndrome and the Warburg effect, due to deficient OXPHOS, the suggestion is that the organism would tend to elevate glycolysis." (PMID 39684297, 2024). "P4 presented developmental delay, which represents the most common symptom in FOXRED1-related iMD, and MRI findings were suggestive of Leigh syndrome." (PMID 38283147, 2023).
developmental delay (2 papers, 2019 to 2023). "Here, we describe a child with ataxia, epilepsy and psychomotor developmental delay carrying two heterozygous FOXRED1 variants, c.920G>A (p.Gly307Glu) and c.733+1G>A." (PMID 31434271, 2019).
lactic acidosis (2 papers, 2019 to 2021). Metabolic acidosis characterized by the accumulation of lactate in the body. "In this study, we reported two Chinese patients with neonatal-onset severe progressive encephalopathy with lactic acidosis and characteristic polycystic encephalomalacia on brain MRI, expanding the clinical and molecular genetic spectrum of FOXRED1-related mitochondrial encephalopathy." (PMID 33613441, 2021).
Obesity (2 papers, 2024 to 2026). Accumulation of substantial excess body fat. "Thus, a novel obesity‐associated TRIM15/YY2/FOXRED1 axis is identified that contributes to the proliferation of EAC." (PMID 41237333, 2026).
fumaric aciduria (1 paper, 2023).
learning disorders (1 paper, 2021). "Like other mitochondrial disorders, there is high clinical heterogeneity in FOXRED1-related mitochondrial disorders, which range from mild learning disorders and clumsiness to severe progressive mitochondrial encephalopathy and even failure to survive." (PMID 33613441, 2021).
Mitochondrial encephalopathy (1 paper, 2021). "In this study, we also reviewed all the data of previously reported patients with mitochondrial encephalopathy caused by mutations in the FOXRED1 gene and summarized the genetic and clinical findings of FOXRED1-related MDs." (PMID 33613441, 2021). "Here, we describe two Chinese patients with compound heterozygous variants in the FOXRED1 gene, both presenting with neonatal onset severe progressive mitochondrial encephalopathy and characteristic neuroimaging of early cerebral atrophy and encephalomalacia." (PMID 33613441, 2021). "All mitochondrial encephalopathy patients with FOXRED1 mutations are inherited in an autosomal recessive pattern." (PMID 33613441, 2021). "To date, nine patients with FOXRED1-related mitochondrial encephalopathy from 8 unrelated families have been reported, including our two cases." (PMID 33613441, 2021). "All previously reported cases with FOXRED1-related mitochondrial encephalopathy were collected using a PubMed search, and their data were reviewed." (PMID 33613441, 2021). "Clinical and genetic characteristics of FOXRED1-related mitochondrial encephalopathy." (PMID 33613441, 2021). "However, only a few patients with mitochondrial encephalopathy due to FOXRED1 defects have been reported." (PMID 33613441, 2021). "No genotype-phenotype correlation seems to exist for FOXRED1-related mitochondrial encephalopathy, similar to many other mitochondrial disorders." (PMID 33613441, 2021).
mitochondrial disease (3 papers, 2019 to 2021). "All the FOXRED1 pathogenic variants identified lead to a loss of complex I activity and mitochondrial disease." (PMID 31434271, 2019).
genetic disease (1 paper, 2024). "For instance, querying “FOXRED1” reveals 45 nonsense variations associated with a single genetic disease." (PMID 39395187, 2024).
tumor (1 paper, 2026). "Mechanistically, TRIM15 degrades YY2 through the proteasome pathway, suppressing FOXRED1 transcription and ultimately accelerating tumor proliferation." (PMID 41237333, 2026). "Further studies revealed that TRIM15 promotes tumor progression by mediating the ubiquitination and subsequent degradation of YY2, disrupting lipid and energy metabolism regulation in EAC cells by inhibiting FOXRED1 transcription." (PMID 41237333, 2026). "Notably, our lipid metabolomics results showed that alterations in YY2 and FOXRED1 significantly affect the abundance of various lipid metabolites in EAC cells, regulating tumor progression mainly through the glycerophospholipid metabolic pathway." (PMID 41237333, 2026).
FOXRED1 also shares sentences with these, for which no sentence is quoted: cancer (2 papers); pulmonary hypertension (2); Ataxia (1); depression (1); Encephalopathy (1); epilepsy (1); esophageal adenocarcinoma (1); glycogen storage diseases (1); metabolic disorders (1); preeclampsia (1); Progressive encephalopathy (1).